SYVN1 (synoviolin 1)
Description:
E3 ubiquitin-protein ligase which accepts ubiquitin specifically from endoplasmic reticulum-associated UBC7 E2 ligase and transfers it to substrates, promoting their degradation. Component of the endoplasmic reticulum quality control (ERQC) system also called ER-associated degradation (ERAD) involved in ubiquitin-dependent degradation of misfolded endoplasmic reticulum proteins. Also promotes the degradation of normal but naturally short-lived proteins such as SGK. Protects cells from ER stress-induced apoptosis. Protects neurons from apoptosis induced by polyglutamine-expanded huntingtin (HTT) or unfolded GPR37 by promoting their degradation. Mediates the ubiquitination and subsequent degradation of cytoplasmic NFE2L1 (By similarity). During the early stage of B cell development, required for degradation of the pre-B cell receptor (pre-BCR) complex, hence supporting further differentiation into mature B cells (By similarity).
Synonyms: HRD1; DER3
Tractability: Antibody: UniProt predicts a signal peptide or a membrane-spanning region; the Human Protein Atlas places it where antibodies can reach. PROTAC: UniProt records ubiquitination sites on it; ubiquitination databases record sites on it; its protein half-life has been measured.
Target class: Enzyme; Transferase
Gene: Protein-coding gene on chromosome 11 (65,121,780 to 65,135,747, reverse strand). Ensembl gene ENSG00000162298.
Subcellular location: Endoplasmic reticulum membrane
Subcellular location (Human Protein Atlas): Nucleoplasm; Endoplasmic reticulum; Plasma membrane
Pathways (Reactome):
Cellular responses to stimuli: XBP1(S) activates chaperone genes
Disease: Hh mutants are degraded by ERAD
Metabolism of proteins: ER Quality Control Compartment (ERQC)
Signal Transduction: Hedgehog ligand biogenesis
Gene Ontology:
Molecular function: ATPase binding; protein binding; protein-folding chaperone binding; ubiquitin protein ligase activity; ubiquitin-specific protease binding; DNA-binding transcription factor binding
Biological process: ERAD pathway; negative regulation of endoplasmic reticulum stress-induced intrinsic apoptotic signaling pathway; protein K48-linked ubiquitination; protein stabilization; protein ubiquitination; retrograde protein transport, ER to cytosol; ubiquitin-dependent protein catabolic process; endoplasmic reticulum mannose trimming; immature B cell differentiation; proteasome-mediated ubiquitin-dependent protein catabolic process
Cellular component: Derlin-1 retrotranslocation complex; endoplasmic reticulum; endoplasmic reticulum membrane; endoplasmic reticulum quality control compartment; Hrd1p ubiquitin ligase complex; Hrd1p ubiquitin ligase ERAD-L complex; luminal surveillance complex; membrane; nucleoplasm; plasma membrane; smooth endoplasmic reticulum
Genetic constraint (gnomAD): Loss-of-function variants: 17 observed, 60.07 expected, observed/expected ratio (o/e) 0.28, 90% interval 0.19 to 0.43. The upper end of that interval is the gene's LOEUF score, 0.43, which puts it in group 1 of 6, group 1 being the genes least tolerant of losing a copy. Missense variants: 622 observed, 809.66 expected, observed/expected ratio (o/e) 0.77, 90% interval 0.72 to 0.82. Synonymous variants: 310 observed, 304.68 expected, observed/expected ratio (o/e) 1.02, 90% interval 0.93 to 1.12.
Homologues: Orthologues: chimpanzee SYVN1 (99% identical), macaque SYVN1 (99% identical), mouse Syvn1 (95% identical), pig SYVN1 (95% identical), rat Syvn1 (95% identical), guinea pig SYVN1 (93% identical), dog SYVN1 (91% identical), rabbit SYVN1 (80% identical), tropical clawed frog syvn1 (74% identical), zebrafish syvn1 (68% identical), Drosophila melanogaster sip3 (48% identical), Caenorhabditis elegans sel-11 (43% identical). Paralogues in human: DZIP3 (22% identical), AMFR (18% identical), RNF145 (17% identical), RNF139 (13% identical).
Diseases named in the same sentence as SYVN1 in open-access papers:
SYVN1 is named in the same sentence as 119 diseases in open-access papers, as found by Europe PMC text mining. Sharing a sentence is not in itself a finding about the gene and the disease. The quoted sentences say what the papers report.
breast carcinoma (15 papers, 2015 to 2026). "Dysregulation of SYVN1 is associated with the biological behaviors of breast cancer, lung cancer, and colon cancer." (PMID 35543347, 2022). "Recent studies have shown that the restoration of CASC2 expression significantly suppresses growth and metastasis in breast cancer cells via regulation of the miR-96-5p/SYVN1 pathway and inactivation of the TGF-β signaling pathway." (PMID 31728180, 2019). "CASC2 overexpression inhibites the viability, migration and invasion, and elevates apoptosis of breast cancer cells through acting as a ceRNA for miR-96 and upregulating synoviolin (SYVN1) expression." (PMID 31728180, 2019). "SYVN1 inhibits breast cancer growth and metastasis through the miR-96-5p/SYVN1 axis." (PMID 35847032, 2022). "Synovial apoptosis inhibitor 1 (SYVN1), an ER-associated degradation (ERAD) E3 ubiquitin ligase, could inhibit the breast cancer cell growth and metastasis through the miR-96-5p/SYVN1 axis." (PMID 31277690, 2019). "E3 ubiquitin ligase HRD1 (HMG-CoA reductase degradation protein 1, alias synoviolin with SYVN1 as the official gene symbol) was found downregulated and acting as a tumor suppressor in breast cancer, while the exact expression profile of HRD1 in different breast cancer subtypes remains unknown." (PMID 33530981, 2021). "After establishing the role of SYVN1 in the degradation of MNK1/2 induced by VNLG-152R, we proceeded to assess the impact of VNLG-152R on canonical pathways relevant to breast cancer." (PMID 37766871, 2023).
hepatocellular carcinoma (10 papers, 2020 to 2026). A malignant tumor that arises from hepatocytes. "On the contrary, the tumor-promoting (oncogenic) effects of SYVN1 have been revealed in colon cancer, lung cancer, and hepatocellular carcinoma." (PMID 37766871, 2023). "We found that circ-0039459 and SYVN1 mRNA were highly expressed, whereas miR-432 was lowly expressed in hepatocellular carcinoma cells and tissues." (PMID 35543347, 2022). "In contrast to its tumor-suppressive activity, SYVN1 exerts tumor-promoting effects through ubiquitination and degradation of tumor-suppressors in different cancers, including colon cancer, prostate cancer, lung cancer, and hepatocellular carcinoma." (PMID 38679705, 2024). "Hence, circ-0039459 can affect the proliferation, apoptosis, migration, and invasion of hepatocellular carcinoma cells through the adsorption of miR-432, thereby regulating the expression of SYVN1." (PMID 35543347, 2022). "Previously, ubiquitinomics analysis showed that SYVN1 is overexpressed in hepatocellular carcinoma (HCC) and promotes tumourigenesis and metastasis." (PMID 38679705, 2024). "Furthermore, SYVN1 overexpression reversed the effect of miR-432 overexpression in hepatoma cells." (PMID 35543347, 2022). "Notably, SYVN1 promoted the tumorigenic phenotype by regulating the ubiquitination and degradation of SIRT2 and PTEN in lung cancer and hepatocellular carcinoma." (PMID 37444412, 2023).
diabetes (9 papers, 2012 to 2026). "Transgenic mice overexpressing SYVN1 and wild-type (WT) mice with streptozotocin-induced diabetes were used in this experiment." (PMID 26358086, 2015). "In the current study, we generated a transgenic mouse line that overexpresses SYVN1 and used these mice to study the protective role of SYVN1 against DR by inducing diabetes using streptozotocin (STZ) injection." (PMID 26358086, 2015). "We delved deeper into the specifics of MAM protein-protein interactions and discovered key connections between many of the altered MAM proteins in diabetes with several major protein regulators of inflammation, diabetes, and/or DR, specifically IL-1β, NFκBIA, FOXO1, SYVN1, STAT4, MAF, and LGALS3." (PMID 36139394, 2022).
liver cancer (8 papers, 2015 to 2026). An epithelial or non-epithelial malignant neoplasm that arises from the liver. "In liver cancer, SYVN1 promotes the proliferation, metastasis, and immune evasion of liver cancer cells through the ubiquitination and degradation of substrate proteins such as PTEN and FoxO1." (PMID 40877231, 2025). "We found circ_0039459 was upregulated in liver cancer tissues and cells, which knockdown inhibited cell metastasis and facilitates apoptosis via regulating the miR-432/SYVN1 axis." (PMID 35543347, 2022). "Previous studies have suggested that E3 ubiquitin-protein ligase SYVN1 expressed highly in liver cancer and interacted with HSP90 to drive metastasis and vascular invasion." (PMID 34820329, 2021). "Moreover, we presented novel mechanisms for LASP1 and SYVN1 to be involved in HBX-mediated GLUD1 inhibition in HBV-induced liver cancer." (PMID 38587834, 2024). "A study has indicated that SYVN1 is related to the growth and metastasis of liver cancer." (PMID 35543347, 2022). "SYVN1 is highly expressed in liver cancer tissues and cells." (PMID 35543347, 2022). "In summary, circ-0039459 plays a carcinogenic effect in liver cancer, and circ-0039459 targets miR-432 to regulate the expression of SYVN1, which may be the mechanism by which circ-0039459 affects the apoptosis, proliferation, invasion, migration, and EMT process of liver tumor cells." (PMID 35543347, 2022). "Further analysis found that SYVN1 overexpression can reverse the effects of miR-432 overexpression on apoptosis, migration, proliferation, invasion, and EMT of liver cancer cells, consistent with previous studies." (PMID 35543347, 2022).
liver cirrhosis (8 papers, 2018 to 2025). "Additionally, synoviolin-1 (also known as Hrd1) is an E3 ligase that has been shown to degrade NRF2 in the endoplasmic reticulum, particularly during liver cirrhosis." (PMID 37840813, 2023).
lung carcinoma (8 papers, 2018 to 2024).
Obesity (7 papers, 2018 to 2025). Accumulation of substantial excess body fat. "On the contrary, other works points towards SYVN1 deletion specifically in the liver as protection against HFD-induced obesity and liver steatosis and insulin resistance in mice." (PMID 36860523, 2023). "Moreover, the SYVN1 enzyme activity inhibitor LS-102, which has potential applications in the study of rheumatoid arthritis and obesity, inhibits cell proliferation induced by SYVN1." (PMID 40877231, 2025).
colon cancer (6 papers, 2022 to 2025). "By other hand, miR396 can affect the expression of the CMKLR1 gene, involved in cardiovascular diseases, and the SYVN1 and SCAMP5 genes, changes in the expression of which are associated with colon cancer and autism, respectively." (PMID 40001983, 2025).
diabetic retinopathy (6 papers, 2015 to 2024). "Synoviolin 1 (SYVN1) was associated with ER stress, chronic inflammation, and vascular overgrowth in diabetic retinopathy (DR)." (PMID 32066502, 2020). "A notable finding was the decreased synoviolin 1 (SYVN1) expression in retinal tissues from HG-induced Müller cell models and STZ-induced diabetic retinopathy mouse models." (PMID 38193803, 2024).
rheumatoid arthritis (6 papers, 2016 to 2025). A chronic, systemic autoimmune disorder characterized by inflammation in the synovial membranes and articular surfaces. "SYVN1 is over-expressed in synoviocytes of patients with rheumatoid arthritis, exacerbating the pathogenesis of the disease." (PMID 35115505, 2022).
Ataxia (5 papers, 2024 to 2026). Ataxia refers to impaired coordination of voluntary muscle movement. "Here, we report the identification of 3 biallelic missense variants of SEL1L and HRD1 (or SYVN1) in 6 children from 3 independent families presenting with developmental delay, intellectual disability, microcephaly, facial dysmorphisms, hypotonia, and/or ataxia." (PMID 37943610, 2024).
triple-negative breast carcinoma (4 papers, 2021 to 2025). An invasive breast carcinoma which is negative for expression of estrogen receptor (ER), progesterone receptor (PR), and human epidermal growth factor receptor 2 (HER2). "Another study revealed that SYVN1 ubiquitylates CPT2 to inhibit fatty acid oxidation and tumorigenesis in triple-negative breast cancer." (PMID 37816756, 2023).
esophageal squamous cell carcinoma (3 papers, 2021 to 2025). Esophageal squamous cell carcinoma (ESCC) is a type of esophageal carcinoma (EC) that can affect any part of the esophagus, but is usually located in the upper or middle third. "Indomethacin, for instance, diminishes the growth and recurrence of esophageal squamous cell carcinoma (ESCC) by enhancing the E3 ligase synovial apoptosis inhibitor 1 (SYVN1)-mediated ubiquitination of integrin αv (ITGAV)." (PMID 39048965, 2024). "It had been reported that ITGAV was a promising therapeutic target for esophageal squamous cell carcinoma (ESCC), as indomethacin can inhibit ESCC growth by binding to ITGAV, promoting SYVN1-mediated ubiquitination of ITGAV, and enhancing cytotoxic CD8+ T cell responses." (PMID 40018050, 2025).
lymphoma (3 papers, 2017 to 2023). A malignant (clonal) proliferation of B- lymphocytes or T- lymphocytes which involves the lymph nodes, bone marrow and/or extranodal sites. "Increasing evidence suggests that SYVN1 is involved in the progression of various malignancies, such as tumours from the liver, breast, and prostate as well as lymphoma." (PMID 37816756, 2023).
osteoarthritis (3 papers, 2018 to 2024). A noninflammatory degenerative joint disease occurring chiefly in older persons, characterized by degeneration of the articular cartilage, hypertrophy of bone at the margins and changes in the synovial membrane. "Overexpression of miR-125b-5p was associated with the pathogenesis of osteoarthritis by down-regulation of SYVN1, reflecting that SYVN1 was closely associated with OA." (PMID 32066502, 2020).
ovarian carcinoma (3 papers, 2023 to 2024). A malignant neoplasm originating from the surface ovarian epithelium. "Although SYVN1 mediates erastin-induced ferroptosis in ovarian cancer cells by facilitating ubiquitination-dependent degradation of SLC7A11, direct evidence for SYVN1-dependent NFE2L2 degradation during ferroptosis remains limited." (PMID 39534872, 2024).
cystic fibrosis (2 papers, 2024). Autosomal recessive disorder caused by pathogenic variants in the CFTR gene (cystic fibrosis transmembrane conductance regulator), which encodes a chloride and bicarbonate channel expressed in epithelial cells, and follow the diagnosis criteria. "In addition, knockout of the ubiquitin ligase SYVN1 or NEDD8 partially restores ΔF508-CFTR-mediated Cl-transport in human cystic fibrosis airway epithelia, indicating the important role of NEDD8 in ΔF508-CFTR-induced cystic fibrosis." (PMID 39697538, 2024).
Hyperglycemia (2 papers, 2015 to 2023). An increased concentration of glucose in the blood. "Our study found that vascular permeability was reduced in diabetic SYVN1 transgenic mice compared with that in diabetic WT mice, suggesting that SYVN1 may confer resistance against increases in retinal vascular permeability caused by hyperglycemia." (PMID 26358086, 2015). "Collectively, these results unveil the Syvn1/Nrf2/GPx4 pathway as a critical mediator of the protective effects of H2S against ferroptosis and apoptosis induced by hyperglycemia and hyperlipidemia in cardiomyocytes." (PMID 37875467, 2023).
lung adenocarcinoma (2 papers, 2020 to 2023). A carcinoma that arises from the lung and is characterized by the presence of malignant glandular epithelial cells. "Importantly, SYVN1 was identified as an E3 ubiquitin ligase that catalyses the nonproteolytic ubiquitylation of MCT4, which regulates glycolytic metabolism and thus controls cell proliferation and the progression of lung adenocarcinoma (LUAD)." (PMID 37816756, 2023). "Taking advantage of human lung adenocarcinoma (LUAD) cells, this study revealed that MCT4 can be polyubiquitylated in a nonproteolytic manner by SYVN1 E3 ubiquitin ligase." (PMID 37816756, 2023).
retinal degeneration (2 papers, 2020 to 2021). Degeneration of the retina. "Furthermore, SORDD1/2 and HRD1/SYVN1 were also able to prevent retinal degeneration in Drosophila with the G69D (glycine to aspartic acid at amino acid residue 69) rhodopsin mutation." (PMID 34381136, 2021).
asthma (1 paper, 2023). "Thus, we thought that the activation of ER stress in asthma partially caused an increase in SYVN1 expression, and the SYVN1 suppressed ER stress response to protect against airway remodeling." (PMID 38041162, 2023). "However, the underlying mechanism of SYVN1 on EMT in asthma is unclear." (PMID 38041162, 2023). "Our results showed that the ER stress in OVA-induced asthma mice was abrogated by SYVN1 overexpression." (PMID 38041162, 2023). "In the present study, an ovalbumin (OVA)-induced murine model was used to evaluate the effect of SYVN1 on asthma." (PMID 38041162, 2023). "Adenoviral vectors overexpressing SYVN1 were constructed and infected into mice to study its role in asthma." (PMID 38041162, 2023). "Taken together, these results show an important effect of SYVN1 on ER stress in asthma." (PMID 38041162, 2023). "Collectively, these results indicate that SYVN1 controls the EMT process in asthma." (PMID 38041162, 2023). "However, the role of SYVN1 in the pathogenesis of asthma is unclear." (PMID 38041162, 2023). "Collectively, our results suggest that SYVN1 promotes SIRT2 ubiquitination and induces inactivation of ER stress, which blocks EMT process and attenuates airway remodeling in asthma." (PMID 38041162, 2023). "In addition, we identify that the expression of SYVN1 is upregulated in asthmatic mice from the GEO dataset (Accession: GSE27066), suggesting possible implications of SYVN1 in the pathogenesis of asthma." (PMID 38041162, 2023).
cervical cancer (1 paper, 2025). A primary or metastatic malignant neoplasm involving the cervix. "Furthermore, in CRC, cervical cancer, and endometrial cancer, m6A/IGF2BP1-mediated mRNA stabilizations of DEAD-box helicase 27 (DDX27), BDNF, and SYVN1 are also vital for tumor cells to enhance epithelial–mesenchymal transition." (PMID 40584294, 2025). "Down-regulation of SYVN1 leads to the accumulation of NLR family pyrin domain containing 3 (NLRP3) protein by suppressing its ubiquitination/proteasomal degradation, leading to the activation of NLRP3/IL-1β/Smad2/3 axis, and eventually, epithelial–mesenchymal transition in cervical cancer." (PMID 40584294, 2025).
cholangiocarcinoma (1 paper, 2024). A carcinoma that arises from the intrahepatic biliary tree (intrahepatic cholangiocarcinoma) or from the junction, or adjacent to the junction, of the right and left hepatic ducts (hilar cholangiocarcinoma). "This shed light on a novel regulatory mechanism involving EIF3B, SYVN1, and PCNA in cholangiocarcinoma pathogenesis." (PMID 38687509, 2024).
chronic asthma (1 paper, 2023). An asthma that is characterized by the development of persistent airway inflammation and recurrent attacks of breathlessness and wheezing, which vary in severity and frequency. "The functional experiments demonstrated that SYVN1 might mediate a protective mechanism on airway remodeling in chronic asthma." (PMID 38041162, 2023).
Cognitive impairment (1 paper, 2025). Abnormal cognition is characterized by deficits in thinking, reasoning, or remembering. "Both genetic knockdown and pharmacological inhibition of ELK1 reduce APP amyloidogenic processing by promoting the SYVN1-mediated ubiquitination and degradation of PS1, thereby inhibiting Aβ generation and alleviating synaptic and cognitive impairments in a mouse model of AD." (PMID 40307574, 2025).